PDGFRA (platelet derived growth factor receptor alpha)
Diseases named in the same sentence as PDGFRA in open-access papers (continued):
Sharing a sentence is not in itself a finding about the gene and the disease.
liver fibrosis (continued). "We also sought to better define the role of PDGFRα in liver fibrosis by utilizing both human specimens and mouse models." (PMID 24667490, 2014). "In summary, our data suggest that PDGFRα has a specific role in liver fibrosis in mice and in humans, and suggest that further mechanistic evaluation of PDGFRα function in the liver has the potential to uncover new anti-fibrotic therapies." (PMID 24667490, 2014). "After confirming that Pdgfrα expression increases with CCl4-induced liver injury, and that PDGFRα-positive HSCs are activated by CCl4 exposure, we utilized PdgfrαWT/nGFPmice to evaluate the functional significance of Pdgfrα expression during liver fibrosis." (PMID 24667490, 2014). "We found that mice with decreased Pdgfrα expression have less liver fibrosis after chronic CCl4 injury." (PMID 24667490, 2014). "Using a variety of experimental approaches, increased PDGFRα was seen in cirrhotic human livers and in mice with chemically-induced liver fibrosis." (PMID 24667490, 2014). "Inhibition of PDGFRα enrichment in serum EVs alleviated liver fibrosis." (PMID 39767572, 2024). "Patients with liver fibrosis also had increased levels of PDGFRα in serum EV." (PMID 35397694, 2022). "In addition, PDGF-BB is involved in promoting the secretion of extracellular vesicles containing PDGFRα, which in turn facilitates the activation of cellular function of hepatic stellate cells, promoting liver fibrosis." (PMID 34335301, 2021). "Deletion of PDGFRα in hepatocytes significantly attenuated TAA-induced liver fibrosis." (PMID 30509307, 2018). "We hypothesized that PDGFRα in hepatocytes in the setting of chronic liver injury plays an important role in liver fibrosis by facilitating intercellular crosstalk between hepatocytes and HSCs." (PMID 30509307, 2018). "However, PDGFRα conditional KO mice showed significantly attenuated liver fibrosis compared to WT mice." (PMID 30509307, 2018). "We hypothesized that upon liver injury, PDGFRα in insulted hepatocytes contributes to liver fibrosis by facilitating intercellular crosstalk between hepatocytes and HSCs." (PMID 30509307, 2018). "The expression of PDGFRα in the tumor sites was associated neither with underlying liver fibrosis/cirrhosis nor with the expression of PDGFRα in adjacent non-tumor sites of the liver." (PMID 28465473, 2017). "Together our data suggest that PDGFRα inhibitors could be an effective means to reduce liver fibrosis in patients." (PMID 24667490, 2014). "We and others posit that selectively targeting PDGFRα in liver fibrosis and cirrhosis could reduce the proliferation, migration, and survival of the activated HSCs cells that contribute to collagen deposition." (PMID 24667490, 2014). "This fibrotic response is reduced in Pdgfrα heterozygous mice, consistent with the hypothesis that liver fibrosis requires upregulation and activation of PDGFRα." (PMID 24667490, 2014). "Therapeutic blockade of PDGFRα signaling may have a broad impact in the treatment of liver fibrosis, as four of the five PDGF ligand dimers, PDGF-AA, -AB, -BB, and –CC, bind and activate PDGFRα." (PMID 24667490, 2014). "Spearman correlation analysis revealed a significant positive association between the infiltration density of inflammatory fibroblasts (α-SMA+PDGFRA+CAFs) and peritumoral collagen deposition area (r = 0.686, p = 0.001), suggesting this subset may directly drive hepatic fibrosis via ECM remodeling." (PMID 41408647, 2025). "ITGAV and PDGFRA are two genes up-regulated, which could promote hepatic fibrosis." (PMID 38549107, 2024). "However, the expression of PDGFRα did not necessarily associated with underlying liver fibrosis/cirrhosis or the expression of PDGFRα in adjacent non-tumor site of the liver." (PMID 28465473, 2017).
liver fibrosis (continued). "In addition, although HCC is often preceded by liver fibrosis where increased PDGFRα expression is frequently detected, association of PDGFRα up-regulation in HCC and the condition of adjacent non-tumor site is to be more thoroughly investigated." (PMID 28465473, 2017). "EVs derived from PDGFRα-overexpressing cells have been shown to enhance HSC migration in vitro and contribute to liver fibrosis in vivo." (PMID 39767572, 2024). "Deletion of PDGFRα in hepatocytes attenuated the upregulation of PDGFRα in HSCs after TAA treatment, resulting in decreased liver fibrosis and HSC activation." (PMID 30509307, 2018). "Therefore, the role of PDGFRα expression in adult hepatocytes in liver fibrosis is unknown." (PMID 30509307, 2018). "While only PDGFRα in HSCs has been thought to play a role in liver fibrosis, we report that PDGFRα is upregulated in injured hepatocytes, which contributes to HSC proliferation, resulting in liver fibrosis." (PMID 30509307, 2018). "PDGFRα in hepatocytes plays an important role in liver fibrosis by inducing HSC activation and proliferation; in vitro, HSCs co-cultured with PDGFRα-deleted hepatocytes exhibited attenuated activation and decreased collagen production." (PMID 30509307, 2018). "HQD down-regulated the expressions of PDGFra, PDGFrb, PDGFb, PDGFd, COL1A1, COL1A2, COL5A2 and THBS1, and TGF-β and PDGF signaling pathways in the DMN-induced liver fibrosis in rats." (PMID 26691002, 2015). "Ten DEGs including PDGFra, PDGFrb, PDGFb, PDGFd, COL1A1, COL1A2, COL5A2, ITGA5, THBS1 and IL1R1, closely related to liver fibrosis, were chosen for the real-time qRT-PCR analysis." (PMID 26691002, 2015). "Considering that platelet-derived growth factor (PDGF)-BB is a key molecule in the process leading to liver fibrosis, it has been reported that PDGF-BB–treated HSCs release PDGF receptor-alpha (PDGFRα)-enriched exosomes, which promote HSC migration and liver fibrosis." (PMID 35185602, 2021). "Livers with hepatitis but not significant liver fibrosis showed elevated PDGFRα expression compared to the normal livers, but col1α(I) expression was not significantly different." (PMID 30509307, 2018). "PDGFRα is reported to be up-regulated in the injured liver with fibrosis and beginning to be recognized as a potential mediator of HSC activation, leading to liver fibrosis." (PMID 28465473, 2017). "The role of PDGFRα in non-cancerous hepatocytes and liver fibrosis is unclear." (PMID 30509307, 2018). "Although PDGFRα expression in HCC may not be the consequence of liver fibrosis/cirrhosis, it should be emphasized that this suggestion does not preclude the possible communication between HSCs and tumor cells in the liver." (PMID 28465473, 2017). "PDGFRs are thought to play a central role in activating HSCs and promoting liver fibrosis and cirrhosis; whether PDGFRα and PDGFRβ play independent roles in fibrogenesis is not known." (PMID 24667490, 2014). "Since PDGFRα, Col1α(I), Lrat, αSMA, and lysyl oxidase homolog 2 (LOXL2) are known as the marker for liver fibrosis, expression of these genes in non-tumor site was assessed in association with the existence of liver cirrhosis." (PMID 28465473, 2017).
soft tissue sarcoma (21 papers, 2013 to 2025). A malignant neoplasm arising from muscle tissue, adipose tissue, blood vessels, fibrous tissue, or other supportive tissues excluding the bones. "Pdgfra encodes platelet-derived growth factor receptor alpha, which is targeted by olaratumab, an antibody approved to treat certain types of soft tissue sarcoma." (PMID 35454087, 2022). "For example, olaratumab is a platelet-derived growth factor receptor alpha (PDGFR-α) blocking antibody that received the FDA approval in 2016 for use in combination with doxorubicin for the treatment of adult patients with advanced soft tissue sarcoma (STS)." (PMID 39086395, 2024). "Further, a PDGFRα monoclonal antibody, olaratumab, in combination with chemotherapy demonstrated clinical benefit in patients with soft tissue sarcoma." (PMID 38611000, 2024). "Promising biomarkers in common and aggressive STS subtypes are TEM1 for myxofibrosarcoma, TEM1, and PDGFRα for undifferentiated soft tissue sarcoma and EGFR for synovial sarcoma." (PMID 33535618, 2021). "More comprehensive preclinical research involving a variety of different experimental approaches is required to fully assess and perhaps confirm the failure of anti-PDGFRA targeting in the field of soft tissue sarcoma." (PMID 31331295, 2019). "In this regard during the writing of this manuscript, Olaratumab, a human IgG1 monoclonal antibody that binds to PDGFRα was approved by the FDA to be used in combination with doxorubicin for the treatment of adult patients with soft tissue sarcoma." (PMID 28219375, 2017). "GISTs are the most common soft tissue sarcoma of the gastrointestinal tract, resulting most commonly from KIT or platelet-derived growth factor receptor alpha (PDGFRalpha)-activating mutations." (PMID 26372813, 2015). "Use case – Soft tissue sarcoma with reported amplification ofKIT,PDGFRA,MDM2,RICTOR andFGF10." (PMID 31608148, 2019). "Pazopanib, a PDGFRα and PDGFRβ/ VEGFR/ c-kit-targeting tyrosine kinase inhibitor, has been approved by Food and Drug Administration (FDA) for soft tissue sarcoma and renal cell carcinoma." (PMID 28511645, 2017). "Notably, TEM1, VEGFR-1, EGFR, VEGFR-2, IGF-1R, PDGFRα, and CD40 are highly expressed in the tumor cells of soft tissue sarcoma." (PMID 40258773, 2025). "In 2017, approval was given to olaratumab (Lartruvo), a targeted antibody against the platelet-derived growth factor receptor alpha (PDGFRα), for patients with soft tissue sarcoma who were left without options to be treated by surgery and radiation." (PMID 33297561, 2020). "Moreover, recent data on olaratumab, a recombinant human IgG1 monoclonal antibody that specifically binds PDGFRA and receptor activation, and its FDA approval, may significantly improve outcome of patients with soft tissue sarcoma." (PMID 28491276, 2017). "Moreover, a trial in participants with soft tissue sarcoma (STS) wherein platelet-derived growth factor (PDGF)/PDGF receptor (PDGFR) signaling plays a significant role, reported a clinical benefit in participants treated with olaratumab (PDGFRα monoclonal antibody) in combination with chemotherapy." (PMID 38611000, 2024). "While the anti-PDGFRA antibody olaratumab failed to confirm an impact on survival in unselected advanced soft tissue sarcoma (STS) patients, the level of expression and the prognosis of platelet-derived growth factor (PDGF) receptors and ligands in STS remain unclear." (PMID 33524869, 2021).
hepatocellular carcinoma (19 papers, 2012 to 2026). A malignant tumor that arises from hepatocytes. "Zhu and colleagues found that overexpression of PDGFRα in the endothelial cells of hepatocellular carcinoma tissues was associated with microvascular invasion and was a predictor of a poor prognosis." (PMID 33568640, 2021). "A previous study revealed that LINC00467 promoted proliferation and invasion, inhibited apoptosis, and contributed to axitinib resistance in hepatocellular carcinoma through miR-509-3p/PDGFRA." (PMID 34094954, 2021). "Among TG livers, PDGFRα/Akt/c-myc/cyclinD1 signaling was a major molecular pathway that drove the development of hepatomas after DEN induction." (PMID 32489479, 2020). "Platelet-derived growth factor receptor alpha (PDGFRα) is suggested as a prognosis marker for hepatocellular carcinoma (HCC)." (PMID 28465473, 2017). "Third, overexpression of PDGFRα in hepatoma cells promotes cell proliferation, migration,invasion and EMT in vitro and tumor growth in vivo." (PMID 25333264, 2014). "In vitro experiments were then performed to further address potential impacts of PDGFRα on biological behavior of hepatoma cells." (PMID 25333264, 2014). "Additionally, stable overexpression of PDGFRα in hepatoma cells promoted cell proliferation, migration, invasion and epithelial-mesenchymal transition in vitro." (PMID 25333264, 2014). "Similarly, an in vivo assay showed that PDGFRα overexpression in hepatoma cells exhibited remarkably tumorigenic potential in tumor size and weight in vivo, which displayed markedly elevated MVD than controls." (PMID 25333264, 2014). "Interestingly, our in vitro study showed that PDGFRα overexpression in hepatoma cells instead of endothelial cells also resulted in increased metastatic propensity." (PMID 25333264, 2014). "And 3G3, a PDGFRα antibody, could inhibit hepatoma cells growth, the mechanism and clinical relevance of which, however, remains unknown." (PMID 25333264, 2014). "Lastly, β-catenin inhibition lead to PDGFRα activation and thus may make the hepatoma cells more amenable to receptor tyrosine kinases inhibition for therapies." (PMID 22761897, 2012). "However, cancerous hepatocytes may show upregulation of PDGFRα, and hepatocellular carcinoma is preceded by chronic liver injury." (PMID 30509307, 2018). "Platelet-derived growth factor receptor alpha (PDGFRA) was shared in pathways of gastric cancer and hepatocellular carcinoma." (PMID 33115518, 2020). "We found decreased E-cadherin and increased vimentin expression in cells with overexpressing PDGFRα, indicating that PDGFRα promoted epithelial-mesenchymal transition (EMT) of hepatoma cells." (PMID 25333264, 2014). "While decreased cell proliferation was observed in hepatoma cells after β-catenin knockdown, PDGF-CC promoted their mitogenesis more robustly only after β-catenin suppression that leads to PDGFRα upregulation." (PMID 22761897, 2012). "The results of target prediction showed that PDGFRA, FLT1, PIK3CD and MET might be the main targets of compound 15 against hepatocellular carcinoma." (PMID 41023382, 2025). "To further ascertain the relevance of PDGFRα signaling in absence of β-catenin, we utilized human hepatoma cells." (PMID 22761897, 2012). "PDGFRA is an angiogenesis‐related gene, and the mRNA expression of PDGFRA and vascular invasion are positively related to HIF‐1alpha in hepatocellular carcinoma (HCC), which could promote tumor inflammation." (PMID 38770632, 2024).
pancreatic cancer (19 papers, 2010 to 2026). "In a pancreatic cancer mouse model, PDGFRα+ CAFs accelerated tumour proliferation, in contrast to normal pancreatic fibroblasts that impeded tumour progression." (PMID 39780187, 2025). "In pancreatic cancer, Platelet Derived Growth Factor Receptor alpha (PDGFRα) and beta (PDGFRβ) are both expressed widely by fibroblasts and CAFs." (PMID 37626931, 2023). "In pancreatic cancer cell lines and pancreatic cancer stem cells (CSCs), vismodegib inhibits cell viability and induces apoptosis increasing Fas expression and decreasing expression of PDGFRα." (PMID 34445078, 2021). "PDGFR/SRC signaling is a therapeutic target in pancreatic cancer with reports of SRC also potentiating PDGFRA activity in other cancer models." (PMID 33213062, 2020). "In a recent analysis of 2,400 pancreatic cancer patients of whom 82% were found to have mutated KRAS, mutations in BRAF, EGFR, HER2, FLT3, HRAS, PDGFRA, and PTEN were identified exclusively in KRAS wild-type patients, and even there, only rarely (8%)." (PMID 26161408, 2015). "Tyrosine kinases are attractive targets for pancreatic cancer therapy because several are over-expressed, including PDGFRα/β, FAK, Src and Lyn." (PMID 20209107, 2010). "PDGFRα can interact with integrin α5β1 to promote cell contraction and reorganization of the ECM, resulting in directional migration of prostate and pancreatic cancer cells." (PMID 39780187, 2025). "Therefore, our studies suggested that PDGFRα and KIT downregulation in pancreatic cancer leads to decreased p70S6K phosphorylation at Ser 418, and increased IRS-1 phosphorylation at Ser 636 via increased PI3K/AKT mTOR/P70S6K signaling." (PMID 27014871, 2016).
leukemia (18 papers, 2007 to 2025). A malignant (clonal) hematologic disorder, involving hematopoietic stem cells and characterized by the presence of primitive or atypical myeloid or lymphoid cells in the bone marrow and the blood. "While it was originally developed for targeting the BCR-ABL gene fusion, it exhibits nanomolar range activity against PDGFRA in leukemia." (PMID 27582545, 2016). "Imatinib mesylate, which is a competitive inhibitor of certain tyrosine kinases including intracellular kinases ABL and the BCR-ABL fusion proteins present in some leukemias, and PDGFRA, is the first effective drug for GIST [, 18]." (PMID 17540038, 2007). "Leukemia patients with overexpression of ITGA2, COL6A1, cyclin D1, PKN1, PDGFRA, or F2R predict or have trends toward worse prognosis." (PMID 41203598, 2025). "Leukemia patients with overexpression of ITGA2, COL6A1, cyclin D1, PKN1, PDGFRA or F2R predicts or has trends toward worse prognosis." (PMID 39764125, 2024). "We exposed four leukemia and four NB cells to multi-kinase (KIT, PDGFRa, and PDGFRb) inhibitor-imatinib in the presence of belinostat or hydrazostat." (PMID 34944663, 2021). "miR-494-3p was mainly paired with immune genes (CD3G, CXCL13, CXCR5, KLRC4), some of which had been annotated as oncogenes in leukemia including IGF1 (DRG; pan-cancer), IKZF3 (driver; leukemia), NABP1 (oncogene; leukemia), and PDGFRA (oncogene; pan-cancer)." (PMID 32605588, 2020). "Quizartinib potently inhibits cellular proliferation and induces apoptosis in leukemia cell lines that are dependent on FLT3, KIT or PDGFRA activity." (PMID 23497317, 2013). "Due to the molecular heterogeneity in AML, genetic abnormalities can vary between individual cases of leukemia, and there may be rare cases where JAK1, PDGFRA and FGFR2 abnormalities are present in CBF-AML." (PMID 37509244, 2023). "We measured the expression of genes coding RTKs: FLT3, KIT exclusively in leukemia cell lines, PDGFRa, AXL in NB, NTRK1, FGFR3, INSR, ROR2, and RET in both NB and leukemia cells by qRT-PCR, which were top-scoring RTK-coding genes among leukemia and NB cell lines." (PMID 34944663, 2021). "While leukemia did not affect the number of mesenchymal stem/stromal cells (MSCs), PDGFRα+Sca-1+ (PαS) mesenchymal cells, CXCL-12 abundant reticular cells and vimentin+ fibroblasts, we observed significantly lower numbers of endothelial and osteoblastic cells." (PMID 29740160, 2018). "This inhibitor was tested to be exclusively specific for PDGFRβ in leukemia and vascular smooth muscle cells, not targeting PDGFRα and c-KIT." (PMID 23900414, 2013).